ERCC4 (ERCC excision repair 4, endonuclease catalytic subunit)
Diseases named in the same sentence as ERCC4 in open-access papers (continued):
Sharing a sentence is not in itself a finding about the gene and the disease.
IgA nephropathy (1 paper, 2025). "This is in line with altered expression of endonuclease ERCC4 in IgA nephropathy and a recent report on gH2A.X accumulation in organoid podocytes incubated with primary or recurrent FSGS plasma." (PMID 40392611, 2025).
ischemic stroke (1 paper, 2022). A stroke disorder caused by obstruction of blood flow to the brain, due to thrombotic (local blood clot formation) or embolic (due to a blood clot or other material traveling from another site) event. "In our previous study, we found that the ERCC4 expression levels were significantly lower in patients with ischemic stroke than in healthy controls, and the 30028T/C polymorphism (rs1799801) of ERCC4 might be associated with ischemic stroke susceptibility." (PMID 36712419, 2022). "It was suggested that ERCC4, as an important component of the ERCC1/ERCC4 heterodimer and a rate-limiting enzyme in the NER pathway, might play a key role in the pathophysiological process of ischemic stroke and that its variations were likely to increase ischemic stroke risk." (PMID 36712419, 2022).
lentivirus infection (1 paper, 2023). Virus diseases caused by the Lentivirus genus. "Except for two cases without cellular materials, ectopic expression of the ERCC4/XPF cDNA by lentivirus infection exclusively rescued the UDS/RRS-deficiency in the patients’ cells, confirming that they are all assigned to the XP-F complementation group." (PMID 37364129, 2023).
liver cancer (1 paper, 2024). An epithelial or non-epithelial malignant neoplasm that arises from the liver. "Our results in yeast were further corroborated upon analysis of whole exome sequenced liver cancers, wherein, tumors with defects in ERCC1 and ERCC4 (NER), FANCD2 (ICL repair) or SPRTN (DPC repair) carried a higher gCn→A mutation load than tumors with no deleterious mutations in these genes." (PMID 38260495, 2024).
nephropathies (1 paper, 2020). "In fact, ERCC1 and ERCC4 play important roles in the development of nephropathies, as demonstrated in mammalian models." (PMID 31924810, 2020).
rectosigmoid adenocarcinoma (1 paper, 2018). An adenocarcinoma arising from the rectosigmoid area. "The only one downregulated NER member was ERCC4 in rectosigmoid adenocarcinoma with fold change of −2.271 (P = 0.009)." (PMID 29568775, 2018).
cancer (54 papers, 2010 to 2025). A tumor composed of atypical neoplastic, often pleomorphic cells that invade other tissues. "In this extensively updated meta-analysis, 11 SNPs were proven to be significantly associated with cancer risk, and four variant-related cancer risks (one for ERCC4 and three for ERCC5) were graded as strong-credibility cumulative epidemiological evidence." (PMID 36033436, 2022). "Several studies have investigated the associations between the ERCC4 polymorphisms and risk of cancers, including cancer of the breast, lung, head and neck, skin, pancreas and bladder cancer, but the results are not consistent." (PMID 22848636, 2012). "Theoretically, genetic variants in the ERCC4/XPF gene could change the regular function of this gene, disturb the DNA repair mechanism and increase cancer risk." (PMID 31040199, 2019). "Single nucleotide polymorphisms (SNPs) in ERCC4 may impact repair capacity and affect cancer susceptibility." (PMID 22848636, 2012). "Thus, an unrecognized function of BRCA2 in regulating transcription elongation is subverted by cancer-causing mutations, in turn provoking the site-specific accumulation of genome-destabilizing R-loops, which can be cleaved by the ERCC4 endonuclease into DNA breaks." (PMID 29386125, 2018). "However, the association of ERCC4 with the prognosis of other cancers was controversial." (PMID 30417012, 2018). "Ki67 and cleaved-caspase 3 immunohistochemical staining indicated increased apoptosis and decreased proliferation of cancer cells following cisplatin treatment upon blockade of the CXCL14/CCR7/STAT3/ERCC4 axis." (PMID 40898244, 2025). "Our analysis revealed that ERCC4 expression is significantly elevated in tumor samples compared to normal tissues and correlated with cancer progression and prognosis." (PMID 40076972, 2025). "This review provides the current research and data on the function of ERCC4, emphasizing its potential therapeutic role in IBD and associated cancer." (PMID 38516408, 2024). "Some of them were cancer-type specific (such as CSF3R), while some others (such as LZTR1 and ERCC4) showed consistent alterations across multiple cancers." (PMID 38067392, 2023). "Meta-analyses aiming to explore the relationship between ERCC4 and ERCC5 variants and the kinds of human cancers were continuously published." (PMID 36033436, 2022). "A total of 19 types of cancer and 24 SNPs of both ERCC4 and ERCC5 were incorporated into meta-analysis because there were at least two serviceable datasets." (PMID 36033436, 2022). "Summary of functional annotations for four single-nucleotide polymorphisms in ERCC4 and ERCC5 with five cancer sites risk (strong epidemiological credibility)." (PMID 36033436, 2022). "The purpose of the current study was to elucidate the role of all studied SNPs in ERCC4 and ERCC5 in the tendency of all implicated types of cancer." (PMID 36033436, 2022). "Because MALAT1 showed a prognostic value in CRC, and it was a well-studied lncRNA in cancers, we selected ERCC4, miR-200c-3p and MALAT1 for verification." (PMID 34993023, 2021). "Potentially pathogenic variants were found in five Cancer Gene Census germline genes: GALNT12, POLE, MPL, ATM, and ERCC4." (PMID 30886832, 2019). "Association between the xeroderma pigmentosum complementation group F (XPF)rs2276466 located in the excision repair cross complementation group 4 (ERCC4) gene and cancer susceptibility has been widely investigated." (PMID 31040199, 2019). "Notably, ERCC1 showed higher expression in cancer tissues than in normal tissues in all cancer types, whereas ERCC4 showed lower expression in cancer tissues than in normal tissues only in KIRC, KIRP, PRAD, THCA, and UCEC." (PMID 39192988, 2024). "It is becoming increasingly clear that although ERCC4 is crucial for genome maintenance, elevated levels of ERCC4 mRNA and protein in cancer patients may paradoxically result in chemotherapy resistance and poor prognosis." (PMID 38516408, 2024).
cancer (continued). "In this updated meta-analysis concerned with ERCC4 and ERCC5 single-nucleotide polymorphisms (SNPs), 160 eligible publications were identified, and we exerted the meta-analysis of correlations between 24 variants and 19 types of cancer." (PMID 36033436, 2022). "ERCC4 and ERCC5 were indispensable component members of the NER pathway; numerous studies were conducted to investigate the correlations between the SNPs of ERCC4 or ERCC5 and the risk of cancers." (PMID 36033436, 2022). "Furthermore, a comprehensive research synopsis with systematic functional annotation has not been performed to evaluate the epidemiological evidence of genetic associations between ERCC4 or ERCC5 genes and the risk of cancers till now." (PMID 36033436, 2022). "ERCC4 has been found with high-expression in cancer tissues, including CRC." (PMID 34993023, 2021). "BRCA2 inactivation by depletion or cancer-causing mutations instigates RNAPII accumulation and R-loop accrual at PPP sites in actively transcribed genes, accompanied by γH2AX formation marking DNA breakage, which is reduced by ERCC4 endonuclease depletion." (PMID 29386125, 2018). "We therefore suggest that future explorative studies of ERCC1 copy number alterations in other cancer types also investigate ERCC4 copy numbers, as these may potentially play a role in ERCC1 expression." (PMID 24144331, 2013). "Taken together, these two potentially functional SNPs (rs2276466 and rs3136038) may alter mRNA expression levels of ERCC4, thereby affecting DRC and modulating cancer susceptibility." (PMID 22848636, 2012). "However, in the literature ERCC2 and ERCC3 have no dominant link with cancer, whereas polymorphisms in ERCC4 have been linked to cancer predisposition." (PMID 38872153, 2024). "BRCA2 inactivation by cancer-associated mutations or RNAi-mediated depletion subverts this mechanism, impeding transcription elongation at the PPP sites of actively transcribed genes, accompanied by R-loop accumulation and DNA breakage mediated by the ERCC4 nuclease." (PMID 29386125, 2018). "We analysed four STAT3 chromatin immunoprecipitation sequencing (ChIP-seq) datasets across three different cancer types and identified two prominent STAT3 binding peaks within the ERCC4 promoter region." (PMID 40898244, 2025). "These 1,670 genes involved well-established cancer-related genes, including MYC, MYB, BRCA2, ERCC4, and MET for s1 subtype and TERT, BCL2, and SUZ12 for s3 subtype." (PMID 36731467, 2023). "As research has progressed, the genomic landscape of cancer has been gradually brought into light, and an increasing number of vital genes shared by various cancers, ERCC4/XPF for example, have been revealed in recent years." (PMID 31040199, 2019). "Three ERCC1 functional SNPs (rs2298881C>A, rs3212986C>A and rs11615G>A) and two XPF/ERCC4 functional SNPs (rs2276466C>G and rs6498486A>C) were genotyped for 1125 gastric adenocarcinoma cases and 1196 cancer-free controls by Taqman assays." (PMID 23166636, 2012). "Of these, seven genes (BRIP1, ERCC4, FANCD2, FANCG, FANCI, MAD2L2, PPP2R2A) were previously related to the platinum sensitivity/resistance of different types of cancer cells, with NPEPPS being reported for the first time as a platinum drug sensitivity regulator." (PMID 35209078, 2022). "Although there have been a few studies on ERCC4 in several cancers, its epigenetic regulation is still not fully understood." (PMID 34993023, 2021).
tumor (32 papers, 2012 to 2025). "Four carriers of germline mutations had additional somatic DDR mutations in the primary tumor: ERCC4; BRCA1, ATM, FANCD2, and MLH1; BRCA1; and BRCA2, RAD50, and ATR." (PMID 36446793, 2022). "For ERCC4 rs1799798 GA/AA carriers, an increased risk of death was observed in older patients (>58 years), non-smokers or former smokers, well-moderately differentiated tumours, and recipients of carboplatin-based or TKI chemotherapies, compared with the GG carriers." (PMID 28878296, 2017). "In summary, our results demonstrate that CXCL14 derived from CAFs within tumor tissues enhances cellular DNA damage repair in a paracrine manner, and its effect on ERCC4 is dose-dependent." (PMID 40898244, 2025). "Since ERCC4 was up-regulated in tumor specimens, we then investigated the clinical significance of ERCC4 expression in CRC patients." (PMID 34993023, 2021). "Moreover, the combination of CXCL14 knockdown in CAFs with ERCC4 knockdown in T24 cells resulted in the most substantial tumor growth inhibition." (PMID 40898244, 2025). "Therefore, we used this criterion and identified four tumors with mutations in ERCC4, one tumor with mutation in ERCC1, two tumors with mutations in FANCD2 of which one also had a mutation in ERCC4 and one sample with a mutation in SPRTN." (PMID 38260495, 2024). "for deleterious ERCC4 variants, the effectiveness of cisplatin is expected for disrupting mutations; PARP inhibitors are selectively toxic to tumours with RAD51C mutations, and tumours with ATM mutations had a positive response to cisplatin, and inhibitors of PARP1, ATR and DNA-PKc." (PMID 32756499, 2020). "Conversely, ERCC4 and ERCC6L2 displayed distinct correlation patterns compared to ERCC6L and the other three genes, suggesting their tumor-suppressing function." (PMID 39582530, 2024). "Substantial CNV deletions were observed in PABPC5, MSH6, IFI16, GNS, ERCC4, BRCA1 and ACACB, while substantial CNV amplification was observed in most tumour types for the remaining genes." (PMID 37660060, 2023). "After analysis of the first 50 tumor specimens, ERCC4/CEN-16 hybridization was terminated due to a lack of aberrations, a finding similar to what was observed in the cell line metaphase panel and also supported by GISTIC analysis in the tumorscape database." (PMID 24144331, 2013). "Given the extensive involvement of metabolic and signal transduction pathways in tumor cells, we aimed to identify the key components of T24 cells responsible for CAF activation and to determine whether the CXCL14/CCR7/STAT3/ERCC4 signaling axis is involved in this process." (PMID 40898244, 2025).
movement disorder (1 paper, 2024). Neurological conditions resulting in abnormal voluntary or involuntary movement, which may impact the speed, fluency, quality and ease of movement. "We report a 62-year-old woman who presented with a movement disorder caused by a homozygous pathogenic variant in the ERCC4 gene." (PMID 39652212, 2024).
ERCC4 also shares sentences with these, for which no sentence is quoted: xeroderma pigmentosum group F (6 papers); autosomal recessive disease (3); genetic diseases (3); head and neck cancer (3); squamous cell carcinoma (3); Xeroderma pigmentosum complementation group F (3); bone marrow failure (2); esophageal cancer (2); Lynch syndrome (2); prostate carcinoma (2); rectal cancer (2); trichothiodystrophy (2); adenocarcinoma (1); adenoma (1); Alagille syndrome (1); alveolar rhabdomyosarcoma (1); anal diseases (1); benign breast disease (1); bone marrow failure syndrome (1); cardiovascular disease (1); Cerebro-Oculo-Facio-Skeletal Syndrome (1); Chronic colitis (1); Crigler-Najjar syndrome (1); DNA‐repair disorders (1); Dubin-Johnson syndrome (1); dysplasia (1); endometrioid carcinomas (1); esophageal squamous cell carcinoma (1); essential thrombocythemia (1); Fanconi anemia complementation group Q (1).
A further 39 diseases each share a sentence with ERCC4 in 1 paper.